EDARADD (EDAR associated via death domain)
Description:
Adapter protein that interacts with EDAR DEATH domain and couples the receptor to EDA signaling pathway during morphogenesis of ectodermal organs. Mediates the activation of NF-kappa-B.
Synonyms: CR; ECTD11A; ECTD11B; ED3; EDA3
Tractability: No criterion of Open Targets' tractability assessment is met for any kind of drug.
Gene: Protein-coding gene on chromosome 1 (236,348,257 to 236,502,915, forward strand). Ensembl gene ENSG00000186197.
Subcellular location: Cytoplasm
Subcellular location (Human Protein Atlas): Nucleoplasm; Cytosol
Pathways (Reactome):
Immune System: TNFs bind their physiological receptors
Gene Ontology:
Molecular function: protein binding
Biological process: signal transduction
Cellular component: cytosol; cytoplasm
Genetic constraint (gnomAD): Loss-of-function variants: 14 observed, 22.09 expected, observed/expected ratio (o/e) 0.63, 90% interval 0.42 to 0.99. The upper end of that interval is the gene's LOEUF score, 0.99, which puts it in group 4 of 6, group 1 being the genes least tolerant of losing a copy. Missense variants: 195 observed, 249.29 expected, observed/expected ratio (o/e) 0.78, 90% interval 0.69 to 0.88. Synonymous variants: 80 observed, 88.17 expected, observed/expected ratio (o/e) 0.91, 90% interval 0.76 to 1.09.
Homologues: Orthologues: chimpanzee EDARADD (99% identical), macaque EDARADD (96% identical), dog EDARADD (88% identical), guinea pig EDARADD (85% identical), rabbit EDARADD (85% identical), pig EDARADD (78% identical), mouse Edaradd (74% identical), rat Edaradd (71% identical).
Diseases named in the same sentence as EDARADD in open-access papers:
EDARADD is named in the same sentence as 21 diseases in open-access papers, as found by Europe PMC text mining. Sharing a sentence is not in itself a finding about the gene and the disease. The quoted sentences say what the papers report.
hypohidrotic ectodermal dysplasia (8 papers, 2012 to 2026). A genetic disorder of ectoderm development characterized by malformation of ectodermal structures such as skin, hair, teeth and sweat glands. "The cg09809672 site is associated with the EDAR-associated death domain gene (EDARADD), which has been linked to ectodermal dysplasia, especially hypohidrotic ectodermal dysplasia." (PMID 31756171, 2019). "One of the most well-characterized forms is hypohidrotic ectodermal dysplasia (HED), typically caused by variants in EDA (ectodysplasin A), EDAR (ectodysplasin A receptor), or EDARADD (EDAR-associated via death domain), and is defined by hypohidrosis, oligodontia with conical teeth, and sparse hair." (PMID 40428341, 2025). "Hypohidrotic ectodermal dysplasia (HED, OMIM 224900) is a rare autosomal recessive syndrome resulting from germline mutations in any of the EDA, EDAR or EDARADD genes in humans." (PMID 36699680, 2022).
ectodermal dysplasia (7 papers, 2012 to 2024). "Mutations in EDARADD (ectodysplasin-A receptor-associated adapter protein) related with ectodermal dysplasia is likely to cause abnormal development of teeth, skin, hair, nails, and sweat glands." (PMID 36683789, 2022). "Only four genes (EDA1, EDAR, EDARADD, and WNT10A) account for 90% of hypohidrotic/anhidrotic ectodermal dysplasia cases." (PMID 38347173, 2024). "Four genes (EDA, EDAR, EDARADD, WNT10A) account for 90% of hypoidrotic/anhidrotic ectodermal dysplasia cases." (PMID 34078430, 2021).
Oligodontia (5 papers, 2015 to 2023). The absence of six or more teeth from the normal series by a failure to develop. "EDARADD is a downstream signaling mediator of EDA and one study reported that a mutation in this gene led to non-syndromic oligodontia." (PMID 26406231, 2015). "In the present study, we investigated six genes (MSX1, PAX9, AXIN2, WNT10A, EDA and EDARADD) in a patient with sporadic non-syndromic oligodontia." (PMID 26406231, 2015). "We found a missense variant in AXIN2, but detected no pathogenic variants in MSX1, PAX9, EDA, EDAR, or EDARADD, genes that previously have been found in nonsyndromic oligodontia." (PMID 32234057, 2020).
tooth agenesis (5 papers, 2015 to 2024). A tooth disease characterized by failure to develop one or more missing teeth. "Mutations in several genes have been associated with familial tooth agenesis, among others MSX1, PAX9, AXIN2, EDA, EDARADD, and EDAR." (PMID 33743023, 2021). "Causative variants in genes of the EDA/EDAR/NF‐κB pathway, such as EDA and EDARADD, have been widely identified in patients with non‐syndromic tooth agenesis (NSTA)." (PMID 33943035, 2021). "Of these, EDA, EDAR, EDARADD, and WNT10A are candidate genes of both non‐syndromic tooth agenesis and syndromic tooth agenesis (STA)." (PMID 33943035, 2021).
prostate carcinoma (2 papers, 2018 to 2020). A carcinoma that arises from epithelial cells of the prostate gland. "Shahabi and colleagues showed that EDARADD expression is upregulated in prostate cancer tissue from patients who develop clinical recurrence." (PMID 32188493, 2020). "We find that five of these genes (IRF2BP2, EDARADD, GPI, HMOX1, KIF3C) were over-expressed in patient samples, and the overexpression was significantly associated with prostate cancer relapse (the onset of metastatic disease) as individual and as a group." (PMID 30478344, 2018).
brain neoplasm (1 paper, 2022). A neoplasm (disease) that involves the brain. "For the PPI network, primarily signals in the malignant brain neoplasm associated with DPP6, RBFOX1, LMF1, and EDARADD to present regulation of alternative splicing of RNA by APP6 and RBFOX1, maturation of specific proteins in ER by LMF1, and activation of NF-κB through EDARADD." (PMID 35887658, 2022). "According to the results of previous research, DNA methylation of EDARADD in brain cancer might predict therapeutic response." (PMID 35887658, 2022). "Other SNP profiles revealed different molecules, including DDP6, NDUFB9, EDARADD, EST1, MC4R, LRP1B, and FRMD3, which perform different roles in brain neoplasms or malignancies." (PMID 35887658, 2022).
dysplasia (1 paper, 2019). A usually neoplastic transformation of the cell, associated with altered architectural tissue patterns. "Hypohidrotic ectodermal dysplasia genes, including EDA, EDAR and EDARADD, were analyzed using next-generation sequencing (NGS)." (PMID 31452656, 2019).
hypohidrosis (1 paper, 2021). diminished sweating in response to appropriate stimuli. "We used targeted next generation sequencing to study EDA, EDAR, EDARADD, and WNT10A genes in 45 Egyptian ED patients with or without hypohidrosis." (PMID 34573371, 2021).
Nail dystrophy (1 paper, 2019). Onychodystrophy (nail dystrophy) refers to nail changes apart from changes of the color (nail dyschromia) and involves partial or complete disruption of the various keratinous layers of the nail plate. "EDAR and EDARADD mutations would cause a clinically indistinguishable phenotype, but are inherited as autosomal, and WNT10A also causes a distinct phenotype with nail dystrophy." (PMID 30397018, 2019).
oropharyngeal cancer (1 paper, 2023). Carcinoma, predominantly squamous cell, arising from the epithelial cells of the oropharynx. "Most of the oral and oropharyngeal cancer samples were unmethylated in almost all the investigated gene promoters: EDARADD, GBP4, HAVCR2, HLA DPB1, IL12RB1, MARCO, and SIGLEC12." (PMID 37175405, 2023).
cancer (3 papers, 2012 to 2023). A tumor composed of atypical neoplastic, often pleomorphic cells that invade other tissues. "Ectodysplasin A-receptor associated death domain (EDARADD) has been analyzed in human cancers in TCGA." (PMID 35887658, 2022).
tumor (2 papers, 2020 to 2025). "In this study, we observed that DNA methylation and gene expression levels of EDARADD are associated with tumour grade, stage, lymph node metastasis and relapse-free survival." (PMID 32188493, 2020). "EDARADD mRNA levels were significantly higher in CAFs from grade group ≥ 4 tumours compared to all other groups of fibroblasts (BPFs, GG ≤ 3 NPFs, GG ≥ 4 NPFs and GG ≤ 3 CAFs), as measured using qPCR." (PMID 32188493, 2020).
EDARADD also shares sentences with these, for which no sentence is quoted: basal cell nevus syndrome (1 paper); blepharocheilodontic syndrome (1); breast carcinoma (1); Floating-Harbor syndrome (1); genetic disorder (1); hypothyroidism (1); incontinentia pigmenti (1); metastatic disease (1); tongue squamous cell carcinoma (1).